LOXL3 (lysyl oxidase like 3)
Description:
Protein-lysine 6-oxidase that mediates the oxidation of peptidyl lysine residues to allysine in target proteins. Catalyzes the post-translational oxidative deamination of peptidyl lysine residues in precursors of elastin and different types of collagens, a prerequisite in the formation of cross-links between collagens and elastin. Required for somite boundary formation by catalyzing oxidation of fibronectin (FN1), enhancing integrin signaling in myofibers and their adhesion to the myotendinous junction (MTJ) (By similarity). Acts as a regulator of inflammatory response by inhibiting differentiation of naive CD4(+) T-cells into T-helper Th17 or regulatory T-cells (Treg): acts by interacting with STAT3 in the nucleus and catalyzing both deacetylation and oxidation of lysine residues on STAT3, leading to disrupt STAT3 dimerization and inhibit STAT3 transcription activity. Oxidation of lysine residues to allysine on STAT3 preferentially takes place on lysine residues that are acetylated. Also able to catalyze deacetylation of lysine residues on STAT3. [Isoform 1]: Shows protein-lysine 6-oxidase activity toward elastin and different types of collagens, with the highest activity toward collagen type VIII. [Isoform 2]: Shows protein-lysine 6-oxidase activity toward elastin and different types of collagens, with the highest activity toward collagen type IV.
Synonyms: LOXL; MYP28
Tractability: Small molecule: a high-quality ligand is known. Antibody: UniProt places it where antibodies can reach, with high confidence; its Gene Ontology location is reachable by antibodies, with high confidence; UniProt predicts a signal peptide or a membrane-spanning region. PROTAC: its protein half-life has been measured; a small molecule that binds it is known.
Target class: Enzyme; Oxidoreductase
Gene: Protein-coding gene on chromosome 2 (74,532,258 to 74,555,718, reverse strand). Ensembl gene ENSG00000115318.
Subcellular location: Secreted, extracellular space; Cytoplasm; Nucleus; Secreted, extracellular space (Isoform 1); Cytoplasm (Isoform 2)
Pathways (Reactome):
Extracellular matrix organization: Crosslinking of collagen fibrils; Elastic fibre formation
Gene Ontology:
Molecular function: protein binding; protein-lysine 6-oxidase activity; copper ion binding; fibronectin binding; oxidoreductase activity, acting on the CH-NH2 group of donors, oxygen as acceptor
Biological process: epithelial to mesenchymal transition; negative regulation of DNA-templated transcription; negative regulation of T-helper 17 cell lineage commitment; peptidyl-lysine oxidation; collagen fibril organization; fibronectin fibril organization; inflammatory response; lung development; positive regulation of integrin-mediated signaling pathway; roof of mouth development; somite development; spinal cord development; animal organ development; tissue development
Cellular component: cytoplasm; extracellular region; nucleus; elastic fiber; extracellular matrix; membrane
Genetic constraint (gnomAD): Loss-of-function variants: 60 observed, 94 expected, observed/expected ratio (o/e) 0.64, 90% interval 0.52 to 0.79. The upper end of that interval is the gene's LOEUF score, 0.79, which puts it in group 3 of 6, group 1 being the genes least tolerant of losing a copy. Missense variants: 874 observed, 1,042 expected, observed/expected ratio (o/e) 0.84, 90% interval 0.79 to 0.89. Synonymous variants: 355 observed, 401.93 expected, observed/expected ratio (o/e) 0.88, 90% interval 0.81 to 0.96.
Homologues: Orthologues: chimpanzee LOXL3 (99% identical), macaque LOXL3 (99% identical), pig LOXL3 (95% identical), rabbit LOXL3 (95% identical), guinea pig LOXL3 (94% identical), dog LOXL3 (93% identical), mouse Loxl3 (93% identical), rat Loxl3 (93% identical), tropical clawed frog loxl3 (71% identical), zebrafish loxl3b (70% identical), zebrafish loxl3a (64% identical). Paralogues in human: LOXL2 (56% identical), LOXL4 (55% identical), DMBT1 (27% identical), CD163 (24% identical), CD163L1 (24% identical), SSC5D (23% identical), PRSS12 (22% identical), LOXL1 (21% identical), SCART1 (21% identical), LOX (19% identical), SSC4D (14% identical), CD6 (13% identical), and 3 more.
Diseases named in the same sentence as LOXL3 in open-access papers:
LOXL3 is named in the same sentence as 71 diseases in open-access papers, as found by Europe PMC text mining. Sharing a sentence is not in itself a finding about the gene and the disease. The quoted sentences say what the papers report.
melanoma (17 papers, 2018 to 2025). A malignant, usually aggressive tumor composed of atypical, neoplastic melanocytes. "In primary melanoma, high LOXL3 expression not only associates with tumor progression and invasiveness but also serves as an independent predictor of poor clinical outcomes." (PMID 41250755, 2025). "Reports from a study on animal models also refer to the interaction of Loxl3 and oncogene Braf, one of the most common mutations found in human melanoma, to facilitate tumor development and progression." (PMID 39273022, 2024). "LOXL3 expression is positively correlated with tumor progression and invasion, and its overexpression is associated with worse prognosis of primary melanoma patients." (PMID 35267510, 2022). "Deletion of Loxl3 and simultaneous activation of Braf and loss of Pten in melanocytes increases melanoma latency and decreases tumor growth, resulting in increased overall survival of mice lacking Loxl3 expression." (PMID 35267510, 2022). "In melanoma, previous reports have pointed out that LOXL3 was associated with the genome stability of melanoma cell and hence impact the mitotic process and apoptosis." (PMID 36324258, 2022). "To further understand the role of Loxl3 in melanoma, we generated a conditional Loxl3-knockout (KO) melanoma mouse model in the context of BrafV600E-activating mutation and Pten loss." (PMID 35267510, 2022). "LOXL3 downregulation inhibited the metastatic ability of melanoma cells, and overexpression of LOXL3 ameliorated the inhibition of melanoma metastasis caused by YTHDF3 downregulation." (PMID 36324258, 2022). "The association of Loxl3 expression with Snail1 and Prrx1 levels seen in primary melanoma-derived cells is reproduced in a collection of established human melanoma cell lines." (PMID 35267510, 2022). "Our current in silico analyses in different tumor samples uncovered a clear association of LOXL3 expression to melanoma with LOXL3 mRNA being particularly higher among melanomas carrying well-known oncogenic mutations." (PMID 29229995, 2018). "Remarkably, the percentage of methylation of LOXL3 regulatory regions inversely associates with LOXL3 expression levels in diverse melanoma cells." (PMID 29229995, 2018). "The LOXL3-SNAIL1-PRRX1 axis may promote the acquisition of malignant phenotypes in melanoma, particularly in the presence of oncogenic BRAF mutations, thereby enhancing tumor cell invasion and migration." (PMID 41250755, 2025). "Moreover, increased LOXL3 gene expression in melanoma is associated with reduced methylation levels in its promoter region." (PMID 41250755, 2025). "We found that LOXL3 is expressed in an ample cohort of primary and malignant human cell lines and uncovered an association of LOXL3 expression with tumor samples carrying melanoma driver mutations." (PMID 35267510, 2022). "At the protein level, we were able to confirm the significant downregulation of Snail1 and Prrx1 upon Loxl3 silencing, suggesting that Loxl3 might control Prrx1 and Snail1 expression in BrafV600E-mutated mouse melanoma cells." (PMID 35267510, 2022). "However, knockdown of LOXL3 causes melanoma cells to display an aberrant DNA damage response (DDR), leading to the accumulation of double-strand breaks (DSB) and aberrant mitosis, and ultimately inducing apoptosis due to increased genomic instability." (PMID 36293126, 2022). "Additionally, in melanoma, LOXL3 maintains genomic stability through an association with oncogenic BRAF and promotes sustained proliferation." (PMID 34360836, 2021). "Furthermore, LOXL3 maintains genomic stability in melanoma by association with oncogenic BRAF in melanogenesis and promotes sustained proliferation." (PMID 34360836, 2021).
melanoma (continued). "Data mining of The Cancer Genome Atlas (TCGA), including whole genome sequencing and transcriptomic profiles of more than 300 cutaneous melanoma patients, revealed upregulated LOXL3 mRNA levels significantly associated with the presence of well-known driver mutations in melanoma." (PMID 29229995, 2018). "Since the involvement of several LOX members in cancer has been extensively characterized, we explored LOXL3 contribution to human cancer by interrogating a comprehensive set of human cancer samples for LOXL3 expression that unveiled an association of LOXL3 to melanoma." (PMID 29229995, 2018). "Therefore, we hypothesized whether Loxl3 might be involved in mouse melanoma cell plasticity underlying Loxl3’s contribution to tumor progression and metastasis." (PMID 35267510, 2022). "Lysyl oxidase-like 3 (LOXL3) is a copper-dependent protein involved in the metastatic potential of melanoma cells via the N6-methyladenosine (m6A) reader YTH N6-methyladenosine RNA-binding protein 3 (YTHDF3)." (PMID 39970778, 2025). "LOXL3 was also demonstrated to control the DNA damage response, thus maintaining genome stability during melanoma progression." (PMID 39970778, 2025). "Immunohistochemical analysis has revealed that LOXL3 serves as a novel prognostic marker in primary melanoma." (PMID 41250755, 2025). "Inhibition of LOXL3-mediated enzymatic activity significantly impairs the invasive and metastatic capacity of melanoma cells." (PMID 41250755, 2025). "Conversely, overexpression of LOXL3 reduces the suppressive effect of YTHDF3 knockdown on melanoma metastasis." (PMID 41250755, 2025). "Animal models with LOXL3 deletion exhibited prolonged onset of melanoma, reduced tumor development, and decreased spread of metastases." (PMID 39273022, 2024). "The RT-qPCR analysis demonstrated a significantly higher LOXL3 fold change gene expression in the BRAF+ melanoma than in the BRAF− melanoma (p = 0.0214), dysplastic nevus (p = 0.0035), and melanoma in situ (p = 0.0024)." (PMID 39273022, 2024). "Upon reviewing the literature, it becomes apparent that certain markers, such as LOXL3, SNAI1, and NES, are associated with melanoma development." (PMID 39273022, 2024). "Prior research has demonstrated that LOXL3 is crucial for the survival of human melanoma cells and the preservation of genomic stability." (PMID 39273022, 2024). "In contrast to human melanoma cell lines in which we found that LOXL3 knockdown resulted in cell death, Loxl3 silencing in mouse melanoma cells reduced cell proliferation without promoting apoptosis." (PMID 35267510, 2022). "To further assess the involvement of Loxl3 in melanoma progression in an immunoproficient setting, we used the highly metastatic B16-F10 mouse melanoma cell line, which can be transplanted into syngeneic C57BL/6 mice." (PMID 35267510, 2022). "Since Loxl3 is required for the migration of MeL3 melanoma cells in vitro, we closely examined all mice injected with MeL3 cells at the endpoint." (PMID 35267510, 2022). "On the other hand, mouse Loxl3 supported melanoma cell migration abilities in vitro and tumor growth in vivo both in MeL3 cells and in our melanoma mouse model, similar to human LOXL3." (PMID 35267510, 2022). "Given the essential role of lysyl oxidase-like 3 (LOXL3) in human melanoma cell survival and its contribution to EMT, we generated mice with conditional melanocyte-specific targeting of Loxl3, concomitant to Braf activation and Pten deletion." (PMID 35267510, 2022). "Collectively, the results depicted thus far, using different melanoma cell lines and both immunodeficient and immunoproficient mice, indicated that Loxl3 contributes to mouse melanomagenesis and metastatic dissemination by tumor-cell-autonomous mechanisms." (PMID 35267510, 2022). "More recently, we unveiled LOXL3’s essential contribution to melanoma cell survival and maintenance of genomic integrity, and showed that LOXL3 is overexpressed in cutaneous melanoma." (PMID 35267510, 2022).
melanoma (continued). "This was supported in vivo by the fact that Loxl3-depleted melanoma cells originated less-proliferative (MeL3) and invasive (B16-F10) tumors, which was recapitulated in the Loxl3 KO mouse melanoma model." (PMID 35267510, 2022). "To understand the molecular mechanisms responsible for the critical role of mouse Loxl3, we explored Loxl3 involvement in melanoma cell plasticity, given our previous data linking LOXL3 to EMT." (PMID 35267510, 2022). "In particular, metastatic lesions in distant lymph nodes were detected in only 4% of mice bearing Loxl3 KO melanomas (1 out of 28 mice) while present in 81% of mice bearing Loxl3 WT melanomas (25 out of 31)." (PMID 35267510, 2022). "All the Braf Pten animals that were subjected to 4-HT treatment developed pigmented lesions that eventually progressed to melanomas with different kinetics depending on their Loxl3 genotype." (PMID 35267510, 2022). "Altogether, these results confirmed that Loxl3 is required for melanoma cell growth both in vivo and in vitro." (PMID 35267510, 2022). "These facts, together with the decrease in tumor growth in the Loxl3 KO animals, provided the first genetic evidence supporting the involvement of Loxl3 in melanoma development in vivo." (PMID 35267510, 2022). "Online bioinformatic tools including GEPIA and UALCAN database indicated that LOXL3 was overexpressed in melanoma, especially metastatic melanoma." (PMID 36324258, 2022). "Collectively, these results demonstrated that via its m6A binding sites, LOXL3 not only had an oncogenic role in the migration and invasion of melanoma but served as an important ‘executor’ of YTHDF3." (PMID 36324258, 2022). "Mechanistically, we showed that LOXL3 is responsible for maintaining melanoma genome stability, since its depletion results in impaired DNA damage response and defective mitotic completion, leading to apoptotic cell death." (PMID 35267510, 2022). "Altogether, these results corroborated that mammalian Loxl3 is involved in melanomagenesis, contributing to the malignant transformation of melanocytes and melanoma metastatic competence." (PMID 35267510, 2022). "Our study revealed the oncogenic role of YTHDF3 and its target LOXL3 in melanoma metastasis and its specific mode of action." (PMID 36324258, 2022). "Upon injection, melanoma-derived cells depleted for Loxl3 formed a lower number of tumors than control cells, and the tumors developed from Loxl3-silenced cells showed increased latency and delayed growth compared to those established from control cells." (PMID 35267510, 2022). "Similar to the expression of YTHDF3, an increased mRNA and protein level of LOXL3 in melanoma cells compared with epidermal melanocytes." (PMID 36324258, 2022). "Our results supported a key role of Loxl3 for melanoma progression, metastatic dissemination, and genomic stability, and supported its contribution to melanoma phenotypic plasticity by modulating the expression of several EMT transcription factors (EMT-TFs)." (PMID 35267510, 2022). "Among various targets identified by multi‐omics analysis, LOXL3 stood out as an optimal target of YTHDF3 in melanoma." (PMID 36324258, 2022). "LOXL3 relevance in melanoma is further supported by a recent analysis of 373 biopsies that correlates LOXL3 expression with tumor progression, invasion, and worse prognosis of primary melanoma patients." (PMID 35267510, 2022). "RT‐qPCR, Western blot and immunohistochemistry were conducted to measure the expression level of YTH N6–methyladenosine RNA binding protein 3 (YTHDF3) and lysyl oxidase–like 3 (LOXL3) in melanoma tissues and cells." (PMID 36324258, 2022). "In summary, our data confirmed the critical action of LOXL3 in promoting melanoma tumor growth and tumor invasion." (PMID 35267510, 2022). "Resembling the human setting, Loxl3 supported genome stability in mouse melanoma-derived cells, and the accumulation of DNA damage upon Loxl3 deletion would thus contribute to impaired tumor cell proliferation." (PMID 35267510, 2022).